AFP (alpha fetoprotein)
Diseases named in the same sentence as AFP in open-access papers (continued):
Sharing a sentence is not in itself a finding about the gene and the disease.
breast carcinoma (continued). "Among them, five markers such as CEA, Ca 15-3, CYFRA 21-1, FERR, and AFP were found to have important differences between breast cancer and benign tumors." (PMID 34335759, 2021). "Similar finding was observed in the detection of alpha-fetoprotein in the cytosol of human breast cancer." (PMID 28467443, 2017). "The role of endogenous estrogens in breast cancer development is well established and AFP has anti-estrogenic activity due to binding of estrogen and their receptor." (PMID 22815728, 2012). "While the role of endogenous estrogens in breast cancer development is well established, the ratio of the estrogen E3 to the anti-estrogen AFP reflects net estrogenic activity." (PMID 22815728, 2012). "Breast cancer risk factors weight, height, race and ethnicity, parity and smoking are associated with infant’s birth weight, maternal concentrations of E3, AFP and PAPP-A and are also breast cancer risk factors." (PMID 22815728, 2012). "The AFP biomarker belongs to aggressive malignant disease, and the fetal protein is used as a constituent member of panels of many combinations of biomarker assays to diagnose various cancers including breast cancer." (PMID 38794187, 2024). "Therefore, it is probably not surprising that it has an excellent tolerability profile, especially considering that the fetal blood levels of AFP reach 10−5 M and the blood levels of AFPep needed for anti-breast cancer activity are only 10−7 M." (PMID 36766292, 2023). "AFP exhibits anti-breast cancer activity in multiple experimental studies." (PMID 36766292, 2023). "AFP detection is also valuable in the diagnosis of early breast cancer." (PMID 36755860, 2022). "Considering that AhR has recently emerged as a physiological regulator of the innate and adaptive immune responses, in a previous publication we described that AFP 464 modulates the immune response in the estrogen-dependent, Tamoxifen-sensitive spontaneous M05 mammary carcinoma model." (PMID 32443455, 2020). "However, lung cancer and breast cancer cells can also take AFP DNA the same way; they might digest the DNAs first and then have those nucleotides used." (PMID 28109303, 2017). "In animal models, AFP can inhibit growth of oestrogen dependent mammary carcinomas in vivo and recently, it has been shown that human AFP peptides may bind the oestrogen receptor and suppress breast cancer cell growth." (PMID 11875734, 2002). "Our findings may be important because they indicate that elevated AFP levels are associated with reduced breast cancer risk, not only among the pregnant women, but also among their female offspring." (PMID 11875734, 2002). "Peptide-based agents like [18F]AFP-SWL, [99mTc]-HYNIC-SWL, and [68Ga]DOTA-SD01 have shown specificity for EphA2 in melanoma, non-small cell lung, and breast cancers, but issues with plasma degradation and low tumor uptake have limited their use 22-24." (PMID 40225586, 2025). "The combination of AFP, CEA, and CA153, as well as AFP and CA153 with CA-125, is reported to have the highest accuracy rate of 80.25% for breast cancer screening." (PMID 40385462, 2025). "Our purpose was to see how other biomarkers, CEA, CA125, and AFP, and blood parameters of parathyroid and thyroid glandular dysfunction interplay with CA15-3, the most commonly used tumor marker in breast cancer." (PMID 38672729, 2024). "The most commonly used biomarkers in relation to breast cancer are carcinoembryonic antigen (CEA), alpha fetoprotein (AFP), carbohydrate antigen 125 (CA125), carbohydrate antigen 199 (CA199), and carbohydrate antigen 15-3 (CA15-3)." (PMID 38672729, 2024). "In this study, high doses of betulinic acid and stigmasterol treatment significantly recovered AFP and CA125 levels in DMBA-induced breast cancer rat models." (PMID 38794187, 2024). "In the subgroup of patients with breast cancer, similar results were obtained with coefficients of correlation of R = 0.83, R = 0.84 and R = 0.85 for CEA, CA 15-3 and AFP, respectively." (PMID 37835844, 2023).
breast carcinoma (continued). "The results showed that there were significant differences in the levels of AFP, CEA, CA153, CA125 and CA199 between the breast cancer group and the benign lesion group." (PMID 36755860, 2022). "In particular, the AFP C-terminal SLiM E489MTPVNPGV497 can inhibit mouse uterine cell proliferation and has shown anticancer effects in MCF-7 breast cancer cells." (PMID 36496998, 2022). "The random forest with CEA, Ca 15-3, CYFRA 21-1, AFP, and FERR showed the optimal combination for distinguishing breast cancer and benign breast disease." (PMID 34335759, 2021). "These five differentiating tumor biomarkers, including CEA, Ca 15-3, CYFRA 21-1, AFP, and FERR showed increased levels in breast cancer patients compared with benign breast disease patients." (PMID 34335759, 2021). "In a separate analysis, mothers whose infants had large birth weights had during pregnancy, elevated E3/AFP ratios and higher PAPP-A concentrations, hormonal conditions favoring breast cancer development and progression." (PMID 22815728, 2012). "They examined the serum levels of animals’—tumor markers alpha-fetoprotein (AFP), carcinoembryonic antigen (CEA), and breast-cancer-specific marker (CA15-3)—and found that tumor-induced rats showed significantly increased levels of these markers compared with control animals." (PMID 39860170, 2025). "These markers (e.g., alpha-fetoprotein (AFP) and cancer antigen 125 (CA125)) are molecules that are produced by cancer cells and could be used to diagnose breast cancer." (PMID 38794187, 2024). "It has been reported that elevated AFP does not correlate with breast cancer, while other studies suggest the contrary." (PMID 38672729, 2024). "Nevertheless, specific tumor uptake of radiolabeled AFP via the AFPR has been demonstrated in vivo, in C3H/Bi mice which overexpress estrogen and aromatase and develop spontaneous mammary tumors, as well as in mice bearing various human prostate, breast and endometrial xenografts." (PMID 37016369, 2023). "AFP, CA153 and CA199 are recommended for clinical diagnosis of breast cancer." (PMID 36755860, 2022). "The detection results of carcinoembryonic antigen (CEA), alpha fetoprotein (AFP), carbohydrate antigen 125 (CA125), carbohydrate antigen 199 (CA199) and carbohydrate antigen 153 (CA153) in patients with breast cancer were significantly higher than those in patients with benign breast tumours." (PMID 36755860, 2022). "Among the different combinations of three parallel detections of breast cancer tumour markers, the highest sensitivity was AFP + CEA + CA153 (83.46%), the highest accuracy was AFP + CEA + CA153 and AFP + CA153 + CA125 (80.25%), and the highest AUC was CEA + CA125 + CA199 (0.922)." (PMID 36755860, 2022). "The increases in AFP, CEA, CA153, CA125 and CA199 tumour markers is closely related to the occurrence of breast cancer, suggesting that five tumour markers are feasible for screening or auxiliary diagnosis of breast cancer." (PMID 36755860, 2022). "In summary, CEA, Ca 15-3, CYFRA 21-1, FERR, and AFP were found to be elevated in nonmetastatic breast cancer patients compared with the benign breast disease controls in our study." (PMID 34335759, 2021). "In this study we have shown, that women delivering large babies have elevated E3/AFP ratio and PAPP-A concentrations, thus likely high net estrogen activity and free insulin-like growth factors concentrations, both favoring breast cancer development and growth." (PMID 22815728, 2012). "Breast carcinoma metastases in endometrium and myometrium were confirmed histopathologically and immunohistochemically with positivity of pancytokeratin and gross cystic disease fluid protein-15 (GCDFP-15) and negativity of Melan A, CD 10, caldesmon, and alpha-fetoprotein (AFP)." (PMID 23573438, 2013).
breast carcinoma (continued). "In summary, the analysis conducted on the levels of CA125, CEA, AFP, fT4, or TSH compared to CA 15-3 levels in cases diagnosed with breast cancer within this specific cohort did not identify any statistically significant associations." (PMID 38672729, 2024). "This study aimed to determine the levels of AFP and CA15-3 with the aim of establishing the presence or absence of tumors and breast cancer." (PMID 39659309, 2024). "Breast cancer patients with either HBV infection or resolved HBV infection, regardless of an elevated AFP level, may receive liver biopsy to avoid unnecessary and inappropriate treatments for metastasis." (PMID 26766567, 2016). "Hepatic lesions detected in patients who previously suffered from breast cancer with either HBV infection or a resolved HBV infection, regardless of AFP levels, may receive liver biopsy to avoid unnecessary and inappropriate treatments for metastasis." (PMID 26766567, 2016).
prostate carcinoma (66 papers, 2011 to 2025). A carcinoma that arises from epithelial cells of the prostate gland. "Elevated CA 19-9, CEA, and AFP are more commonly associated with a gastrointestinal tumor; high levels of prostate-specific antigen (PSA) indicate prostate cancer." (PMID 36550523, 2022). "Huh7 and Hep3b are AFP-producing HCC cells, SK-HEP-1 is a non–AFP-producing HCC cell line, PC-3 is a non–AFP-producing prostate cancer cell line, and THLE-3 is a normal human hepatocyte cell line." (PMID 35857843, 2022). "In prostate cancer, prostate-specific antigen, in testicular cancer human choriogonadotropin and alpha-fetoprotein play important roles in the daily decision making." (PMID 24069434, 2013). "Cancer-associated blood biomarkers have been identified in a few cancers such as prostate specific antigen (PSA) in prostate cancer and alpha fetoprotein in some liver and germline cancers." (PMID 21589655, 2011). "Furthermore, patients with high prostate carcinoma-related mediators (prostate-specific antigen, carcinoembryonic antigen, or alpha-fetoprotein) were excluded from this study." (PMID 34577895, 2021). "However, AFP is associated with liver metastasis, and TPSA is associated with benign prostatic hyperplasia, prostate cancer, and bone metastasis." (PMID 32685054, 2020). "However, clinically effective prognostic predictors have not yet been established as for other cancers, such as PSA for prostate cancer and AFP or hCG for testicular tumors." (PMID 31038863, 2019). "The existence of this reverse transport was indicated by the appearance of increased tumour marker levels (AFP, PSA) and of the secretory protein autotaxin in the circulation as a result of iRGD administration to mice with HCC or prostate cancer, respectively." (PMID 38889481, 2024). "N-glycosylated antigens have been widely used as biomarkers for different types of cancers: alpha-fetoprotein (AFP) for HCC, PSA for prostate cancer, and carbohydrate antigen 19-9 (CA19-9) for CCA." (PMID 36890858, 2023). "This suggests that we must consider that regular monitoring of serum AFP levels could potentially affect the psychological well-being of patients, as suggested for PSA in prostate cancer." (PMID 39741695, 2024). "In its first proof-of-concept application, MiChip can simultaneously detect three serum protein biomarkers: carcinoembryonic antigen (CEA), AFP, and prostate-specific antigen (PSA), all of which are commonly used in clinical tests for colorectal, hepatocellular, and prostate cancers, respectively." (PMID 36986729, 2023). "Some serum glycoprotein biomarkers, such as carcino-embryonic antigen (CEA), carbohydrate antigens 19-9 (CA19-9) and 125 (CA125), alpha-fetoprotein (AFP), and prostate-specific antigen (PSA) have been found to be useful in the initial detection of colon, ovarian, and prostate cancers." (PMID 31167407, 2019). "We not only analysed the expression levels of CFTR in HT-29 cells, HIF-1α in HEK-293T cells, GAPDH in liver tissue of mouse, and serum AFP in HCC patients, but also the glycosylation changes in the sera of prostate cancer patients, in combination with the optimised fixation method." (PMID 31040299, 2019). "Similarly to the use of the AFP promoter and enhancer for HCC, prostate-specific antigen promoters have been used for prostate cancer, while E2F and telomerase reverse transcriptase promoters are used for various types of tumors." (PMID 25667643, 2015).
lung carcinoma (64 papers, 2008 to 2025). "Based on these data, AFP is a suitable marker for screening for OM of lung cancer, with risk of OM increased in patients with serum concentrations of AFP ≥ 0.54 ng/ml." (PMID 34595214, 2021). "However, in lung cancer, AFP is associated with liver metastasis." (PMID 31218849, 2020). "Another study demonstrated the predictive value of AFP in assessing ocular metastasis in lung cancer." (PMID 40430002, 2025). "Especially when used in combination with other tumor markers or molecular indicators, AFP holds potential for improving the accuracy of both diagnosis and prognosis in lung cancer." (PMID 40430002, 2025). "Elevated AFP levels are used for diagnosis, monitoring, and prognostic evaluation in testicular, ovarian, gastric, colorectal, pancreatic, and lung cancers." (PMID 40430002, 2025). "AFP is frequently produced by the fetal liver and yolk sac and is a common marker for gastrointestinal tumors, gallbladder cancer, and lung cancer." (PMID 40406247, 2025). "Overexpression of AFP has been identified in certain rare subtypes of lung cancer, suggesting its potential utility in both diagnosis and prognosis." (PMID 40430002, 2025). "Hepatoid adenocarcinoma of the lung (HAL) is an extremely rare tumor type, which was first reported as an Alpha-fetoprotein (AFP)-producing lung cancer by Ysunami." (PMID 39968074, 2025). "Binary logistic regression analysis indicated that CA-199, CA-153, AFP, CEA, and CYRFA21-1 were independent risk factors for lung cancer metastasis." (PMID 34595214, 2021). "Our results show that CYFRA21-1, AFP, CA-153, CEA, and CA-199 levels are associated with OM of lung cancer, and can be used as independent risk factors." (PMID 34595214, 2021). "Binary logistic regression analysis demonstrated that CA-199, CA-153, AFP, CEA, and CYFRA21-1 were independent risk factors for lung cancer metastasis." (PMID 34595214, 2021). "Hepatoid adenocarcinoma of the lung (HAL) is a rare malignant tumor that is defined as a primary alpha-fetoprotein (AFP)-producing lung carcinoma." (PMID 33585692, 2021). "However, the predicted probability of developing lung cancer increased to the range of 0.22 to 11.58% in 5-years and the range of 0.51% to 24.86% in 10-years for the addition of one to five risk factors (BMI, positive family history of lung cancer, AFP, CEA, and MMEF)." (PMID 27805040, 2016). "Our model incorporated several unique predictors of lung cancer risk, including MMEF as an index of airway obstruction, and the serum markers CEA, bilirubin, AFP, and CRP." (PMID 27805040, 2016). "AFP-producing lung cancers are usually adenocarcinomas, with a small proportion being large-cell carcinomas and squamous-cell carcinomas." (PMID 22559879, 2012). "Histologically, adenocarcinoma (often poorly differentiated adenocarcinoma) accounts for the most of AFP-producing lung cancers." (PMID 21554678, 2011). "Because AFP-producing lung cancer has scarcely been reported, the clinical features of this type of lung cancer are still unclear." (PMID 21554678, 2011). "Furthermore, the accuracy of the present biomarkers, like α-fetoprotein (AFP) and AFP-L3, in detecting lung cancer is only moderate." (PMID 38799446, 2024). "Lung adenocarcinoma that produces alpha-fetoprotein (AFP) is a rare type of lung cancer." (PMID 33607799, 2021). "A number of diagnostic biomarkers for lung cancer have been suggested, including carcinoembryonic antigen (CEA), neuron-specific enolase (NSE), cytokeratin 19 (CYFRA-21-1), alpha-fetoprotein (AFP), serum carbohydrateantigen-125 (CA-125), carbohydrate antigen-19.9 (CA-19.9), and ferritin." (PMID 31976313, 2020). "In addition, the diagnosis of PM was based on the results from imaging studies and AFP serum level, which were sensitive enough to detect most primary lung cancers." (PMID 29416782, 2018). "Patients with primary lung carcinoma and testicular metastasis showed significant elevation of AFP." (PMID 28240047, 2017).